INS (insulin)
Diseases named in the same sentence as INS in open-access papers (continued):
Sharing a sentence is not in itself a finding about the gene and the disease.
Obesity (continued). "Intranasal (IN) administration of insulin decreases appetite in humans, but the underlying mechanisms are unclear, and it is unknown whether IN insulin affects the food intake of women with obesity." (PMID 35397638, 2022). "Glucose, insulin, and gut hormone levels are all linked and frequently dysregulated in obesity." (PMID 35464026, 2022). "Moreover, the metabolic alterations (including insulin sensitivity, insulin secretion, and insulin clearance) that cause different types of dysglycemia in people with obesity are unclear." (PMID 34905513, 2022). "Previous studies have cited impaired insulin balance and its-related disorders, including hyperinsulinemia, which may be important causes of increased risk of obesity and another unhealthy metabolic status." (PMID 35578225, 2022). "Increasing plasma NEFA levels in obesity may lead to the persistent loss of function of beta-cells, causing severe dysfunction in glucose-stimulated insulin secretion pathways and impaired insulin biosynthesis." (PMID 35959181, 2022). "Overexpression of miR-107 may cause an imbalance of glucose homeostasis, obesity, and dyslipidemia, by regulating insulin sensitivity through the insulin signaling pathway." (PMID 35454146, 2022). "Our data suggest that a sympathetic activity–induced augmentation of NEFA and cytokine load within the islet proximity may contribute to obesity-linked transition from insulin hypersecretion to beta-cell failure." (PMID 36138030, 2022). "In addition to the known relationship between general obesity and the risk of BC, central obesity and circulating fasting insulin and glucose have been connected to the development of this prevalent malignancy." (PMID 35145826, 2022). "Furthermore, an obesity-induced increase in leptin, insulin, and proinflammatory cytokine levels can cause hypogonadism." (PMID 36431285, 2022). "Hormones, especially leptin, insulin, and adrenal hormones, have been associated with satiety, glucose homeostasis, and adipogenesis, while hypothyroidism impairs energy metabolism, favoring obesity." (PMID 35631188, 2022). "Several previous studies have reported that, in addition to energy intake, the high amount of added sugar in sugared beverages may lead to a high glycemic load and insulin response, thereby increasing the risk of obesity." (PMID 36145061, 2022). "Moreover, in these experiments, obesity was related to both insulin and acetylcholine signalling defects, i.e., obesity caused a resistance to both hormones." (PMID 36670938, 2022). "Therefore, the current evidence has proven the efficacy of IF in the improvement of muscle function in obesity patients, which probably is involved in attenuating the impaired calcium signaling pathway or/and glucose uptake caused by insulin insensitivity." (PMID 35267959, 2022). "It has been observed in other studies with overweight or obese individuals, that increased cholesterol synthesis marker (lathosterol) is associated with increased resistance to insulin, increased inflammatory activity, and, consequently, obesity is considered indicative of high cardiovascular risk." (PMID 36233298, 2022). "As a result, decreased AMPK action in obesity may have causal roles in ceramide accumulation, thereby decreasing insulin sensitivity in multiple organs." (PMID 35789435, 2022). "This is a unique system to study solely the IL-6 trans-signalling, without the classic signalling activation, during patho-physiological conditions, including, in our case, obesity associated with insulin signalling and glucose metabolism distortion, as well as physical exercise." (PMID 36387898, 2022). "Leukotriene is directly associated with obesity, inflammatory pathways, and response to insulin." (PMID 36458093, 2022).
Obesity (continued). "Excessive weight, obesity, and weight loss through energy restriction can lead to metabolic changes of glucose and lipid that may ultimate result in changes of glucose, insulin, glucagon, and triglyceride in the blood, most of which are “IMAT contributors”8." (PMID 36437293, 2022). "Indeed, all evidence pointed to a substantial link between obesity and cancer, caused not only by well-known factors such as chronic inflammation, but also by insulin resistance, adipokine circuit changes, and microbiome dysregulation." (PMID 35399507, 2022). "T2D is characterized by hyperglycemia as a consequence of systemic inflammation, oxidative stress decreased insulin sensitivity in adipose tissue, liver and muscle implicated in obesity, and reduced secretion of insulin as a result of pancreatic β cell dysfunction." (PMID 36141277, 2022). "Fasting insulin was also strongly and positively associated with elevated endometrial cancer susceptibility in two-sample MR with mediation analyses further highlighting hyper-insulinaemia as a potential driver of the obesity-endometrial cancer link." (PMID 36558416, 2022). "Resistance to insulin, altered adipocytokine components, inflammatory response, and their combinations have been suggested as mechanisms underlying the relationship between obesity and thyroid cancer risk." (PMID 36230635, 2022). "Many obesity-associated metabolic phenotypes were correlated with Bacteroides such as B. uniformis and B. caccae, and B. acidifaciens can prevent obesity and improve insulin sensitivity in mice." (PMID 36407511, 2022). "Furthermore, elevated levels of leptin associated with obesity can inhibit LH-stimulated estradiol production in granulosa cells, as well as inhibit the insulin-induced ovarian steroidogenesis, thus impeding follicle development." (PMID 36139133, 2022). "Therefore, impairments in the central signaling pathways of insulin and leptin are associated with energy imbalance and obesity development." (PMID 35445066, 2022). "Though the genus Ruminiclostridium 5 is known to produce SCFAs in the colon, it has been linked to obesity and cardiometabolic traits in children with normal weight and obesity, showing that the relative abundance of Ruminiclostridium 5 is associated with obesity and fasting plasma insulin." (PMID 36532542, 2022). "We summarized the association between the IFN family and obesity as well as insulin sensitivity." (PMID 36552805, 2022). "Additionally, long-term insulin use can cause a series of side effects such as obesity, hypoglycemia, hyperinsulinemia, and injection site pain." (PMID 36032108, 2022). "In addition to the influence of proinflammatory cytokines such as IL-6 or TNF-alpha, growth-stimulating effects of various obesity-associated hormones such as leptin, estrogen, or insulin have been well described." (PMID 36231132, 2022). "In this work, we evaluated the effect of MTF and the effect of an adiponectin analog as another insulin-sensitizing agent on the expression of molecules associated with adiponectin and insulin signaling pathways in endometrial tissue and endometrial cells under obesity conditions." (PMID 35409282, 2022). "In addition to the lack of control of the mechanisms of the hypothalamic–pituitary axis of hunger and satiety, triggered by increased resistance to leptin and insulin, predisposing to obesity." (PMID 36361448, 2022). "It seems that inositol beneficial effect on obesity and the associated disorders may be related to its involvement in insulin signaling and improving insulin sensitivity." (PMID 35664247, 2022). "There is an ongoing debate over whether obesity in humans is caused by insulin dysregulation or vice versa." (PMID 35883323, 2022). "Both neurotrophic factors have a positive association with insulin and obesity measures." (PMID 35626286, 2022).
Obesity (continued). "Higher fasting insulin and c-reactive protein are associated with higher body mass index (BMI) and all-cause mortality, so may confound the association between obesity and mortality." (PMID 36030344, 2022). "In obese individuals, the body’s lipid metabolism capacity is reduced, the body becomes lipotoxic, and insulin signaling becomes impaired, causing the body to become IR, which leads to the further accumulation of lipids and subsequently increases obesity." (PMID 36531167, 2022). "Extracellular vesicles are normally filtered by liver CRIg+ macrophages and the adoptive transfer of mEVs to CRIg–/– mice potentiated microbial-derived product transport to distal tissues contributing to obesity-associated tissue inflammation and insulin resistance." (PMID 35291443, 2022). "Since obesity is closely associated with glucose intolerance, we next determined whether these sigma-receptor knockout mice had altered glucose or insulin tolerance after 6 weeks of HFD." (PMID 36142759, 2022). "On the contrary, APN deficiency in gonadally intact mice mitigates obesity development and positively influences insulin sensitivity in a HFD setting, which is likely explained by subtle changes in food intake and energy expenditure leading to a lower net energy balance over time." (PMID 36198723, 2022). "Obesity is associated with increased fatty acid production, altered adipokine secretion, and increased adipocyte production of inflammatory cytokines, all of which can inhibit insulin signaling through modification of various intracellular pathways." (PMID 35725477, 2022). "Pro-inflammatory cytokines are released from tissue macrophages and directly reduce insulin sensitivity, which may contribute to the development of IR associated with obesity." (PMID 36581855, 2022). "‘A growing body of evidence suggests that dietary strategies with the aim to reduce postprandial insulin response and increase fat oxidation, and that tend to restore metabolic flexibility, have a place in the prevention and treatment of obesity and associated metabolic disorders’." (PMID 36035748, 2022). "Consequently, these AT macrophages secrete high levels of pro-inflammatory cytokines, resulting in obesity-associated chronic low-grade inflammation (meta-inflammation) and impairments in insulin signaling." (PMID 35909571, 2022). "On the other hand, the reduction in irisin levels observed in patients with long-lasting obesity and T2D could play a causal role in insulin secretory dysfunction." (PMID 35628332, 2022). "Although our results showed that BMI greater than or equal to 25 does not have a statistically relevant association with glucose homeostasis (fasting glucose, fasting insulin, and HbA1c levels), overweight and obesity are associated with higher total cholesterol and triglyceride levels." (PMID 35254432, 2022). "However, due to aberrant insulin signaling, Tregs associated with obesity exacerbate adipose inflammation through alterations in cytokine production." (PMID 35752704, 2022). "Furthermore, visceral fat is considered an important risk factor in the development of resistance to insulin and is present in various stages of obesity-induced hippocampal dysfunction, which is a brain area involved in memory processes." (PMID 36479300, 2022). "Peripherally, ANXA1 may act in an endocrine manner to regulate inflammatory biomarkers to dampen inflammation, regulate insulin secretion and improve the metabolic profile to reduce the risk of developing obesity associated co-morbidities." (PMID 35684160, 2022). "Alarin has been implicated in obesity and insulin sensitivity." (PMID 35493201, 2022). "In addition, the addition of DATS during pregnancy enhanced the lipid metabolism of the maternal, improved the insulin resistance of the obese mothers, and alleviated the placental vascular dysplasia caused by the obesity of the mothers." (PMID 35684030, 2022).
Obesity (continued). "Emphasizing the importance of weight loss for glycemic control in T2DM, a recently published study demonstrated reduced blood glucose and improved secretion and sensitivity to insulin in patients with DM and obesity undergoing weight loss, either through diet or surgery (gastric bypass)." (PMID 36992732, 2022). "An indication of oxidative stress in this study is the augmented hepatic levels of MDA which is associated with depleted levels of GSH, an essential cellular antioxidant that acts against redox imbalance restoring insulin sensitivity in obesity-associated metabolic syndrome." (PMID 35720181, 2022). "An interesting study was conducted in 2018, in Quebec, Canada, on the assessment of dietary intakes of macronutrients and food groups in the association with insulin sensitivity and insulin secretion over a 2-year period in children with a family history of obesity." (PMID 36364954, 2022). "Moreover, T2DM and concomitant obesity are associated with BC risk and prognosis, where insulin directly boosts cell proliferation." (PMID 35145826, 2022). "However, a deranged function of the two enzymes has also been related to increased levels of insulin, fatty acids, and proinflammatory mediators, linking these hallmarks of obesity-associated metabolic impairment to BCAA catabolism and the LACA." (PMID 36686477, 2022). "Obesity causes increased insulin release due to decreased insulin responsiveness." (PMID 35326592, 2022). "Being overweight is a problem that has been made worse by our lifestyles, which include too much sedentary activity and packaged foodstuffs, as well as our inherent inclination to accumulate fat in reaction to insulin - obesity and being overweight raise the risk of illness and mortality." (PMID 36540483, 2022). "Due to the relatively high obesity prevalence in this pediatric population, the present study suggests that increased breakfast consumption could lead to lower insulin levels in a high-risk pediatric population." (PMID 35684120, 2022). "Whether activation of the sympathetic nervous system and insulin resistance are the causes or consequences of obesity is uncertain." (PMID 35512304, 2022). "Resistance to insulin then may lower the pulse amplitude of the luteinizing hormone as well as the mean release of luteinizing hormone in the pituitary gland in obesity which may cause luteal phase impairment." (PMID 36320802, 2022). "In this study, we present the Mixed Meal Model a computational model introducing the systemic postprandial interplay between triglyceride and NEFA in the glucose-insulin system with the aim of capturing the pre-clinical deteriorations in metabolic resilience that underly overweight and obesity." (PMID 36281448, 2022). "Patients with morbid obesity and T2DM demonstrated high levels of liver fat fraction, and we showed that hepatic steatosis, but not the degree of liver fibrosis, was associated with different measures of insulin sensitivity in patients with severe obesity and T2DM." (PMID 36336684, 2022). "Similarly, TLR4 gene mutation protected against HFD-induced obesity and promoted insulin signalling." (PMID 34184629, 2022). "Altogether, butyrate may counteract obesity‐associated mitochondrial dysfunction and muscle atrophy and can indirectly increase insulin‐mediated glucose disposal in the muscle tissue." (PMID 35856338, 2022). "It is acknowledged that overweight and obesity have been proven to be risk factors for T2D, and they can reduce insulin sensitivity to peripheral tissues and cause β-cell dysfunction through numerous pathogenetic mechanisms, playing a considerable role in the initiation and development of T2D." (PMID 36159296, 2022). "Adiponectin is the most abundant protein secreted by WAT, has insulin-sensitizing, anti-atherogenic and anti-inflammatory effects, and its circulating levels are positively associated with insulin sensitivity and decrease with obesity, being thus proposed as a therapeutic target." (PMID 35216509, 2022).
Obesity (continued). "TRF may be an effective nutritional approach for weight loss, and the amelioration of glycemic control and insulin sensitivity in individuals with overweight/obesity." (PMID 36432465, 2022). "Elevated ceramide concentrations, together with their significant correlation with IR parameters in pediatric patients with obesity, were suggested to be associated with molecular pathways involved in insulin signaling impairment strongly linked to the pathogenesis of NAFLD." (PMID 35185803, 2022). "Given that adiponectin stimulates insulin secretion, enhances its signaling and inhibits gluconeogenesis, by decreasing the adiponectin production, IL-8 may play a crucial role in obesity-linked IR and GDM." (PMID 36498901, 2022). "Thus, the combination of different polygenic risk pathways, including insulin action, insulin secretion, obesity, fat distribution, and lipids/liver function, forms an overall palette of risk." (PMID 35292083, 2022). "In addition, obesity is associated with ultrastructural alterations in the skeletal muscle capillary endothelium, which impair trans-endothelial insulin transport, a critical step in skeletal muscle glucose uptake." (PMID 35055038, 2022). "Hormonal changes, such as TSH and insulin, are also associated with obesity." (PMID 36389127, 2022). "Associations between micronutrient deficiencies and obesity have been reported in various populations, and such deficiencies may affect leptin and insulin metabolisms." (PMID 35498399, 2022). "Adipose tissue‐derived small EVs are a possible regulator of obesity‐associated dysfunction, and small EV signalling might act as an important link between obesity and peripheral tissue insulin sensitivity." (PMID 35293040, 2022). "Finally, IL-21 has been shown to be increased in adipose tissue during obesity, and IL-21 deficiency leads to the expansion of adipose tissue Treg cells and preserves insulin sensitivity." (PMID 34837070, 2022). "Indeed, such diets can cause or contribute to excessive insulin secretion, increased oxidative stress, beta-cell dysfunction, and an increased risk of obesity and type 2 diabetes." (PMID 36311488, 2022). "However, specific racial ethnicities, such as Pima Indians, known to have very high insulin levels have an increased risk of developing obesity." (PMID 35578225, 2022). "Disruption of insulin signaling by obesity has been linked with airway hyperreactivity and asthma." (PMID 36107629, 2022). "In addition, recent studies showed that mice deficient in this enzyme were resistant to diet-induced obesity, increased insulin and leptin sensitivity." (PMID 35637957, 2022). "In addition, increasing sleep by 30 min for 3 days over the weekend in healthy industrial workers and individuals susceptible to obesity significantly increased insulin sensitivity and had a restorative effect of sleep on metabolic homeostasis." (PMID 36292943, 2022). "Recent reports from the HAPO follow-up study in which the children are now aged 10–14 years also identify maternal glucose levels, independent of BMI, being associated with increased childhood overweight/obesity and with a child’s glucose and insulin sensitivity." (PMID 35928679, 2022). "Furthermore, homozygous mice were much heavier and fatter than heterozygous and wild-type mice and secreted more insulin, consistent with obesity-associated insulin hypersecretion." (PMID 35054781, 2022). "RXRα is a transcription factor that regulates expression of genes including PPARα involved in whole-body lipid and glucose metabolism, insulin sensitivity and adipogenesis, suggesting an association between early life epigenetic modifications and later obesity risk." (PMID 36329895, 2022). "In previous investigations carried out by our group, it was observed that an obesity state could exacerbate the failures associated with insulin action in endometrial tissue from women with PCOS." (PMID 35409282, 2022).